HMOX1 (heme oxygenase 1)
Diseases named in the same sentence as HMOX1 in open-access papers (continued):
Sharing a sentence is not in itself a finding about the gene and the disease.
subarachnoid hemorrhage (20 papers, 2016 to 2026). A serious neurological disorder characterized by intracranial hemorrhage into the subarachnoid space. "MLT was found to inhibit ferroptosis in subarachnoid haemorrhage-mediated neuronal injury by activating genes such as Nrf2 and Heme oxygenase-1 (HO-1)." (PMID 38846099, 2024). "We found increased levels of heme oxygenase-1 and biliverdin reductase protein in the choroid plexus over the entire period following subarachnoid hemorrhage induction." (PMID 33328892, 2020). "Immunostaining for heme oxygenase-1 was found in both cuboidal epithelial cells and epiplexus Kolmer cells of the choroid plexus of naïve, subarachnoid hemorrhage, and artificial cerebrospinal fluid animals." (PMID 33328892, 2020). "In conclusion, we found increased levels of heme oxygenase-1 and biliverdin reductase proteins in the choroid plexus over the entire period following subarachnoid hemorrhage induction." (PMID 33328892, 2020). "The number of heme oxygenase-1 positive Kolmer cells was significantly higher at 3 days (p < 0.05) after subarachnoid hemorrhage induction when compared to artificial cerebrospinal fluid group of animals at the same time point." (PMID 33328892, 2020). "The level of heme oxygenase-1 was the highest early (1 and 3 days) after subarachnoid hemorrhage indicating its importance in hemoglobin degradation." (PMID 33328892, 2020). "Using heme oxygenase-1 immunostaining, we detected its highest immunopositivity in both choroid plexus epithelial cells and Kolmer cells early after subarachnoid hemorrhage (1 and 3 days), supporting a role for heme oxygenase-1 in hemoglobin degradation." (PMID 33328892, 2020). "Changes in heme oxygenase-1 levels in the choroid plexus of subarachnoid hemorrhage and artificial cerebrospinal fluid animals were confirmed by Western blot analysis." (PMID 33328892, 2020). "Our results of immunohistochemical analysis confirmed by Western blot assessment demonstrated increased levels of total heme oxygenase-1 protein in the choroid plexus following induction of subarachnoid hemorrhage." (PMID 33328892, 2020). "In contrast to biliverdin reductase, heme oxygenase-1 expression shifted from epiplexus macrophages in the early stage, to choroid plexus epithelial cells in the later stage following subarachnoid hemorrhage induction." (PMID 33328892, 2020). "The intensity of heme oxygenase-1 immunofluorescence was significantly increased one-day (p < 0.05) after induction of subarachnoid hemorrhage when compared with artificial cerebrospinal fluid animals at the same time point." (PMID 33328892, 2020). "Double immunohistochemical staining demonstrated that heme oxygenase-1 positive cells in the epiplexus position from subarachnoid hemorrhage animals displayed positivity for both activated (ED1+) and resident (ED2+) macrophages." (PMID 33328892, 2020). "The level of heme oxygenase-1 was the highest early after subarachnoid hemorrhage indicating its importance in hemoglobin degradation." (PMID 33328892, 2020). "Therefore, the aim of our present experiments was to monitor the time-course of heme oxygenase-1 and biliverdin reductase protein levels in the choroid plexus following subarachnoid hemorrhage or application of artificial cerebrospinal fluid as control." (PMID 33328892, 2020). "Levels of heme oxygenase-1 protein were significantly increased in the choroid plexus removed at 1 (2.5-fold; p < 0.05), 3 (2.4-fold; p < 0.05), and 7 days (1.9-fold; p < 0.05) after subarachnoid hemorrhage induction." (PMID 33328892, 2020). "Immunohistochemical and Western blot analyses were used to monitor changes in the of heme oxygenase-1 and biliverdin reductase levels in the rat choroid plexus after induction of subarachnoid hemorrhage or artificial cerebrospinal fluid application for 1, 3, and 7 days." (PMID 33328892, 2020).
subarachnoid hemorrhage (continued). "The results of increased immunostaining for heme oxygenase-1 and biliverdin reductase in choroid plexus epithelial cells may indicate their involvement in heme degradation early after experimental subarachnoid hemorrhage (1 and 3 days)." (PMID 33328892, 2020). "In our study, we found increased levels of heme oxygenase-1 and biliverdin reductase in choroid plexus cells after induction of subarachnoid hemorrhage, but increased heme oxygenase-1 was also detected on the first day after artificial cerebrospinal fluid application." (PMID 33328892, 2020). "The number of heme oxygenase-1 positive Kolmer cells was significantly increased in the choroid plexus of animals 1 (n = 166.3 ± 40/mm2; p < 0.05) and 3 days (n = 203.1 ± 18.5/mm2; p < 0.01) following subarachnoid hemorrhage induction when compared to naïve animals (n = 64 ± 25.2/mm2)." (PMID 33328892, 2020). "Therefore, the increased level of heme oxygenase-1 in choroid plexus epithelial cells after subarachnoid hemorrhage we found in our experimental animals may contribute to maintaining blood-cerebrospinal fluid barrier integrity." (PMID 33328892, 2020). "Interestingly, increased heme oxygenase-1 was also detected in the choroid plexus after artificial cerebrospinal fluid application for one-day, indicating that the sudden elevation of intracranial pressure after subarachnoid hemorrhage may also contribute to alteration of heme oxygenase-1 levels." (PMID 33328892, 2020). "Therefore, the aim of present study was to investigate changes in protein levels of heme oxygenase-1 and biliverdin reductase in the rat choroid plexus after experimental subarachnoid hemorrhage induced by injection of non-heparinized autologous blood to the cisterna magna." (PMID 33328892, 2020). "Our results suggest that heme oxygenase-1 and biliverdin reductase are involved not only in hemoglobin degradation but probably also in protecting choroid plexus epithelial cells and the blood-cerebrospinal fluid barrier from the negative effects of subarachnoid hemorrhage." (PMID 33328892, 2020).
cervical carcinoma (19 papers, 2014 to 2025). A carcinoma arising from either the exocervical squamous epithelium or the endocervical glandular epithelium. "Several of these proteins are implicated in cervical cancer, including Ptgs2 (up), Hmox1 (up), Mkl1 (down), and Arhgap5 (down) (60, –, 63)." (PMID 41165329, 2025). "We performed a similar analysis on our RNA-seq analysis and identified several genes that are also implicated in cervical cancer and HPV infection, including Krt16 (up), Krt6a (up), Hmox1 (up), and Krt15 (down)." (PMID 41165329, 2025). "Metformin has been reported to inhibit heme oxygenase-1 (HO-1) expression in cancer cells, including cervical cancer HeLa cells." (PMID 34067321, 2021). "Another downstream effector, heme oxygenase–1 (HO–1), exhibits context-dependent roles in cervical cancer: while the NRF2/HO–1 pathway generally suppresses ferroptosis due to its antioxidative function, HO–1 can switch to a pro-ferroptotic role under certain stress conditions." (PMID 40895556, 2025).
neuropathy (19 papers, 2016 to 2026). A disorder affecting the nervous system that manifests with pain, tingling, numbness, and/or muscle weakness. "In Neuropathy the expression of NFE2L2 & HMOX1 is down-regulated in sciatic nerves of diabetic mice and its expression aids in reduction of formalin induced inflammatory pain and thereby indicating its role in preventing sensory motor alterations." (PMID 28761062, 2017).
renal failure (19 papers, 2008 to 2026). "Using an inducible Hmox1 deletion model (Hmox1R26Δ/Δ), we demonstrate that Hmox1 expression is essential for preventing heme-induced kidney failure." (PMID 41550715, 2026).
type 1 diabetes (19 papers, 2012 to 2025). "We studied the association of HMOX1 polymorphisms and HO-1 serum concentrations with vascular complications and all-cause mortality in individuals with type 1 diabetes (T1D)." (PMID 40826355, 2025). "In type 1 diabetes, curcumin, as a heme oxygenase-1 (HO-1) inducer, improved blood glucose levels (27.5% lower) and insulin secretion (66.67% higher) in diabetic rats, as well as regulating blood lipids and attenuating lipid peroxidation damage in the pancreas and liver." (PMID 40909997, 2025). "Interruption of glucose supply with reduced PPP and NADPH generation, such as during a hypoglycaemic event in type 1 diabetes (where induction of Sod2 and Hmox-1 is impaired), will further hamper detoxification of ROS and the induction of antioxidant defence proteins." (PMID 37015997, 2023).
chronic myeloid leukemia (18 papers, 2012 to 2023). "We have shown that Hsp32, also known as heme oxygenase-1 (HO-1), serves as survival factor and potential target in Ph+ chronic myeloid leukemia." (PMID 24681707, 2014).
lung adenocarcinoma (18 papers, 2011 to 2025). A carcinoma that arises from the lung and is characterized by the presence of malignant glandular epithelial cells. "We previously reported that loss of SMARCA4 in lung adenocarcinomas led to increased NRF2 signaling, including expression of the NRF2 targets HMOX1 and GSTM4." (PMID 38358974, 2024). "A study in Lung adenocarcinoma cells revealed high glucose levels induced increased heme oxygenase-1 (HO-1), and subsequent increases in tumor cell invasiveness via increased PI3K/akt signaling." (PMID 34277624, 2021). "Subsequently, it is verified that 9 core targets for ginseng treatment of lung adenocarcinoma, namely, JUN, IL-1β, IL-2, ICAM1, HMOX1, MMP9, MMP2, PTGS2, and TNF, are closely related to the proliferation, migration, and apoptosis of lung adenocarcinoma cells." (PMID 32802118, 2020). "In addition, HMOX1 expression has been found to significantly enhance EMT and promote lung adenocarcinoma metastasis." (PMID 37382594, 2023). "Meanwhile, according to the results of qRT-PCR, it is speculated that ginseng can treat lung adenocarcinoma by up-regulated JUN, IL-1β, IL-2, ICAM1, HMOX1, MMP9, and MMP2 targets and down-regulated PTGS2 and TNF genes." (PMID 32802118, 2020).
lupus (18 papers, 2018 to 2025). "Supporting this evidence, the presence of a long allele in a (GT)n microsatellite polymorphism in Hmox-1 gene promoter leading to decreased expression of HO-1, gives rise to a pronounced risk and higher susceptibility to develop autoimmune disease, such systemic lupus erythematosus." (PMID 39611159, 2024). "Similarly, the anti-inflammatory effects of HMOX1 induction were observed in FcγRIIb−/− mice, which are a model of systemic lupus erythematosus (SLE)." (PMID 30258436, 2018). "DHA treatment increased the expression of Nrf2 and its target gene heme oxygenase-1 (HO-1) in myeloid-derived suppressor cells (MDSCs) in systemic lupus erythematosus (SLE) mice and delayed the aging of MDSCs." (PMID 39524446, 2024).
prostate tumor (18 papers, 2012 to 2025). "HMOX1, whose expression has been linked to arsenic-related oxidative stress response, has a recently identified role in prostate tumor progression." (PMID 26588813, 2016). "Consistent with the in vitro findings, HMOX1 expression was noticeably increased in the S.C treatment group.Overall, these results strongly indicate that S.C-induced ferroptosis attenuates prostate tumor growth both in vitro and in vivo." (PMID 38195593, 2024). "The researchers also treated metastatic prostate tumor cells with adipocyte-conditioned media and found that the expression of FABP4, IL-1β, and hemeoxygenase-1 (HMOX1) was upregulated." (PMID 36060264, 2022). "A direct implication of Hmox1 expression in bone remodeling and communication between bone and prostate tumor cells has previously been suggested, without determining its importance in osteocytes." (PMID 39814705, 2025).
thyroid cancer (18 papers, 2018 to 2025). "Previous studies showed that HMOX1 was associated with advanced tumor stage in thyroid cancer." (PMID 36510497, 2022). "However, recent research has demonstrated that ALKBH5, an RNA demethylase homologous to AlkB, can impede the progression of thyroid cancer by inducing ferroptosis in thyroid cancer cells via the TIAM1-Nrf2/Heme Oxygenase 1 (HO-1) axis, as evidenced by both in vitro and in vivo studies." (PMID 39917169, 2025).
fibrosis (17 papers, 2010 to 2025). the formation of excess fibrous connective tissue in an organ or tissue in a reparative or reactive process. "Among the antioxidants, heme oxygenase-1 (HO-1) has been highlighted in several fibrosis." (PMID 40118823, 2025).
pneumonia (17 papers, 2015 to 2025). An acute, acute and chronic, or chronic inflammation focally or diffusely affecting the lung parenchyma, caused by an infection in one or both of the lungs (by bacteria, viruses, fungi, or mycoplasma.). "One study looked for an association between HMOX1 promoters and pneumonia." (PMID 35551540, 2022). "In our opinion, this is the first study to identify SNPs in antioxidant (SOD1, CAT, GPX1, NOS, HMOX1, and NQO1) and immunological (IL-1α, IL1B, IL6, TNF-α, IL10, LFA-1, CR2, IL17, IL13, DEFB123, SCART1, and ICAM1) genes as potential suspects for pneumonia resistance/susceptibility in Barki ewes." (PMID 40221769, 2025). "Heme oxygenase-1 (HO-1) is a rate-limiting enzyme in the process of heme catabolism and is a strong negative regulator of oxidative stress in the endotoxins of ALI and pneumonia." (PMID 37753078, 2023). "The activation of the Nrf2/heme oxygenase 1 (HO-1) and Toll-like receptor (TLR)/mitogen activated protein kinase (MAPK)/nuclear factor kappa B (NF-κB) signaling pathways is involved in IV replication and IV-related pneumonia." (PMID 32689931, 2020).
Anxiety (15 papers, 2016 to 2025). Intense feelings of nervousness, tension, or panic often arise in response to interpersonal stresses. "Unsaturated fatty acids interact with membrane phospholipids to form structural modifiers, which increase membrane flow and permeability, help regulate NRF1/HMOX1 signaling pathway, reduce oxidative stress in vivo, and relieve anxiety symptoms." (PMID 38547138, 2024).
autoimmune disease (15 papers, 2014 to 2025). A disorder resulting from loss of function or tissue destruction of an organ or multiple organs, arising from humoral or cellular immune responses of the individual to their own tissue constituents. "The induction of HMOX1 activity by various natural products has become an important therapeutic target for combating certain neurodegenerative and other autoimmune diseases." (PMID 38254662, 2024). "As emphasized above, HMOX1 is inducible by a variety of natural products and is an important chemotherapeutic target for the prevention and treatment of many neurodegenerative and other autoimmune diseases." (PMID 38254662, 2024). "Heme oxygenase 1 (HO-1) is a protective cytokine with antioxidant, anti-apoptotic and anti-inflammatory effects, and has been shown to be a potential therapeutic target for autoimmune diseases." (PMID 35784335, 2022).
hemorrhagic stroke (15 papers, 2011 to 2024). A stroke caused by a bleed on the brain. "The heme oxygenase-1 (HO-1) enzyme pathway is of crucial importance in the removal of toxic blood components and regulation of neuroinflammation following hemorrhagic stroke." (PMID 38104143, 2023). "Overall, these findings suggest that loss of CDNF decreases mRNA levels of Hmox1 at the early stage of ICH, but increases hematoma accumulation at 3 days post hemorrhagic stroke." (PMID 36792604, 2023). "In Cav-1 knockout mice, there is a reduction in heme oxygenase-1 (HO-1), macrophage inflammatory protein 2, MMP-9, and COX-2 during hemorrhagic stroke, leading to decreased immune cell infiltration and mitigated hemin-induced neuronal toxicity, ultimately improving brain damage." (PMID 38922036, 2024). "In addition, our previous study revealed that heme oxygenase-1 (Hmox1) is significantly downregulated in the hemorrhagic striatum of Cdnf−/− mice, indicating that the absence of CDNF reduces the induction of Hmox1 after hemorrhagic stroke." (PMID 39256999, 2024).
parasitemia (15 papers, 2013 to 2025). "Cluster MCODE8 included IL6, CREB1, and HMOX1, which were associated with molecular pathway for oxidative stress (WP5477), parasitic infection pathways (R-HSA-9824443), and leishmania infection (R-HSA-9658195)." (PMID 40528239, 2025). "However, when the relationships between antioxidant transcript abundance and parasitemia were considered at E15.5 in the E6.5 infection group, Hmox1 and Cat positively correlated with placental parasitemia." (PMID 35312688, 2022). "On the day before preterm delivery, E6.5 infected mice did not experience significant upregulation of the inflammatory or antioxidant gene transcripts examined; however, peripheral and placental parasitemia correlated positively with Il1β, Cox1, Cat, and Hmox1 placental transcript abundance." (PMID 35312688, 2022). "When the relationship between parasite burden and antioxidant gene transcript expression was considered, Cat and Hmox1 transcripts were positively correlated with placental parasitemia at sacrifice and Hmox1 shared this relationship with peripheral parasitemia AUC as well." (PMID 35312688, 2022). "Additionally, Hmox1 positively correlated with peripheral parasitemia AUC." (PMID 35312688, 2022). "The antioxidant CoPP is known to act through Nrf2 activation to activate antioxidant defenses, particularly the expression of HO-1 (heme oxygenase-1) and was previously used by us in T. cruzi infection by Y strain in C57BL/6 mice, reducing parasitemia and macrophage parasitism." (PMID 39509468, 2024).
tuberculosis (15 papers, 2013 to 2023). A chronic, recurrent infection caused by the bacterium Mycobacterium tuberculosis. "The antioxidant enzyme heme oxygenase-1 (HO-1) is implicated in the pathogenesis of tuberculosis (TB) and has been proposed as a biomarker of active disease." (PMID 28553288, 2017). "Chitinase, Indoleamine 2,3-dioxygenesae-1 (IDO-1) and heme oxygenase-1 (HO-1) are candidate diagnostic biomarkers for tuberculosis (TB)." (PMID 36814914, 2023). "Heme oxygenase-1 (HO-1) is a cytoprotective enzyme that controls inflammation and redox homeostasis; however, its role in tuberculosis (TB) is unclear." (PMID 30428359, 2018). "Heme oxygenase-1 (HO-1) is a cytoprotective enzyme that controls inflammatory responses and redox homeostasis; however, its role during pulmonary tuberculosis (TB) remains unclear." (PMID 30428359, 2018).
cerebral infarction (14 papers, 2010 to 2024). An ischemic condition of the brain, producing a persistent focal neurological deficit in the area of distribution of the cerebral arteries. "Significant remission of cerebral infarction was observed in the Kolaviron and quercetin treatment groups, which might be linked to the role of quercetin in the Sirt1/nuclear factor-erythroid 2-related factor 2 (Nrf2)/heme oxygenase-1 (HO-1) signaling cascade." (PMID 35662707, 2022). "Heme oxygenase-1 (HO-1) has been reported to have the most AREs in its promoter, making it a promising therapeutic target against brain injury in cerebral infarction." (PMID 33935731, 2021).
iron overload (14 papers, 2016 to 2025). "HMOX1 also plays a crucial role in iron metabolism by catalyzing the breakdown of heme into biliverdin, carbon monoxide (CO), and iron, thereby contributing to cellular iron homeostasis, and can promote ferroptosis by inducing iron overload." (PMID 39524143, 2024).